GJC2 (gap junction protein gamma 2)
Description:
One gap junction consists of a cluster of closely packed pairs of transmembrane channels, the connexons, through which materials of low MW diffuse from one cell to a neighboring cell. May play a role in myelination in central and peripheral nervous systems.
Synonyms: Cx46.6; Cx47; GJA12; SPG44; HLD2; LMPH1C; LMPHM3; PMLDAR
Tractability: Antibody: UniProt places it where antibodies can reach, with medium confidence; UniProt predicts a signal peptide or a membrane-spanning region; its Gene Ontology location is reachable by antibodies, with medium confidence; the Human Protein Atlas places it where antibodies can reach.
Gene: Protein-coding gene on chromosome 1 (228,149,930 to 228,159,826, forward strand). Ensembl gene ENSG00000198835.
Subcellular location: Cell membrane; Cell junction, gap junction
Subcellular location (Human Protein Atlas): Cytosol; Plasma membrane
Pathways (Reactome):
Vesicle-mediated transport: Gap junction assembly
Gene Ontology:
Molecular function: gap junction channel activity involved in cell communication by electrical coupling; gap junction channel activity
Biological process: cell communication by electrical coupling; cell-cell signaling; cell communication; transmembrane transport
Cellular component: gap junction; plasma membrane; connexin complex; myelin sheath
Genetic constraint (gnomAD): Loss-of-function variants: 0 observed, 1.36 expected, observed/expected ratio (o/e) 0, 90% interval 0 to 1.6. That is too few expected variants to judge how well the gene tolerates losing a copy. Missense variants: 633 observed, 544.19 expected, observed/expected ratio (o/e) 1.16, 90% interval 1.09 to 1.24. Synonymous variants: 330 observed, 259.69 expected, observed/expected ratio (o/e) 1.27, 90% interval 1.16 to 1.39.
Gene-disease validity (ClinGen):
ClinGen rates the evidence that GJC2 causes each of these diseases.
hypomyelinating leukodystrophy 2 (autosomal recessive): Definitive.
Homologues: Orthologues: chimpanzee GJC2 (99% identical), macaque GJC2 (98% identical), rat Gjc2 (86% identical), mouse Gjc2 (85% identical), pig GJC2 (82% identical), dog GJC2 (80% identical), guinea pig GJC2 (72% identical), tropical clawed frog gjc2 (52% identical), zebrafish gjc2 (49% identical). Paralogues in human: GJC1 (44% identical), GJA3 (29% identical), GJD2 (28% identical), GJA8 (27% identical), GJA5 (26% identical), GJA4 (26% identical), GJA10 (25% identical), GJA1 (24% identical), GJA9 (24% identical), GJD3 (23% identical), GJC3 (22% identical), GJD4 (22% identical), and 8 more.
Diseases named in the same sentence as GJC2 in open-access papers:
GJC2 is named in the same sentence as 51 diseases in open-access papers, as found by Europe PMC text mining. Sharing a sentence is not in itself a finding about the gene and the disease. The quoted sentences say what the papers report.
lymphedema (20 papers, 2013 to 2026). Excess fluid collection in tissues, causing swelling. "The association between lymphedema and GJC2 (Cx47) mutations in humans is puzzling and can tentatively be attributed to a reduced number of LVs in those patients and/or to venous valve insufficiency." (PMID 40720769, 2025). "Variants in CX43, encoded by GJA1, and CX47, encoded by GJC2, cause lymphedema in humans, which can be a clinical manifestation of CCLA." (PMID 38618951, 2024). "Missense mutations in Cx43 (GJA1) and Cx47 (GJC2) are each linked to the development of lymphedema in humans, and women with mutations in GJC2 have an increased likelihood of developing lymphedema after breast cancer surgery." (PMID 39074069, 2024). "The dominant inheritance pattern of GJC2 associated lymphedema makes it likely that this disorder is due to a gain of function." (PMID 37189458, 2023). "Dominant mutations in GJC2 also lead to hereditary (primary) lymphedema and some variants in GJC2 are a susceptibility factor for secondary lymphedema after breast cancer surgery." (PMID 37189458, 2023). "In a case-control study Finegold and colleagues sequenced 81 breast cancer patients with secondary lymphedema and 108 control breast cancer patients for mutations in GJC2." (PMID 34072103, 2021). "Although mutations in gap junction protein gamma-2 (GJC2), the gene encoding Cx47, were the first shown to be implicated in lymphedema, Cx47 was only observed in a subset of LECs at upstream sides of lymphatic valves of embryonic mice." (PMID 34072103, 2021). "This is surprising since mutations in GJC2 have been linked to primary and secondary lymphedema in patients." (PMID 28732089, 2017). "Interestingly, Cx43 deficiency in mice also led to abnormal lymphatic development, including defective valve formation, while GJC2 (encoding Cx47) was found to be mutated in lymphedema patients." (PMID 22922986, 2013). "However, lymphedema could potentially develop in patients with GJC2 mutations if dysfunctional venous valves produce venous insufficiency that results in excess filtration from blood capillaries and overwhelms the transport capacity of the lymphatic system." (PMID 40720769, 2025). "Readers interested in further information on the role of GJC2 and other connexins in lymphatic function and lymphedema are referred to a recent review on this topic." (PMID 37189458, 2023). "Mutations in genes encoding the connexins 47 and 37, namely gap junction protein gamma 2 (GJC2) and gap junction protein alpha 4 (GJA4), have been linked to both primary and secondary lymphedema." (PMID 32300557, 2020). "GJA4 was chosen because it encodes Cx37; other studies have already described that two genes (GJC2 encoding connexin 47 and MET gene) also involved in junction formation have mutations associated with the predisposition to secondary lymphedema." (PMID 29470392, 2018). "Indeed, mutations in the GJC2 and GJA1 genes, encoding for Cx47 and Cx43, respectively, have been linked to primary and secondary lymphedema in various families and populations, which is of major importance for the stratification of lymphedema patients." (PMID 34072103, 2021). "The GJC2 variant affects the second transmembrane domain of connexin 47, whereas the OBSCN variant lies in immunoglobulin-like domain 55 of obscurin, a large cytoskeletal signaling protein not previously implicated in lymphedema." (PMID 41530801, 2026). "Following WES analysis of a subset of individuals, a novel mutation in GJC2 (c.287G > T, p.Gly96Val) and a mutation in OBSCN (c.22393T > A, p.Phe7465Ile)—a gene not previously implicated in lymphedema—were identified." (PMID 41530801, 2026). "However, it is important to note that certain mutations, such as those in connexin-47 (GJC2), can cause severe valve defects and lymphedema in humans, despite having no apparent effect in mice." (PMID 41186588, 2026).
lymphedema (continued). "GJC2 mutations have also been described in patients suffering from Pelizaeus-Merzbacher-like disease (PMLD), a hypomyelinating leukoencephalopathy, in which lymphedema does not occur." (PMID 34072103, 2021).
Pelizaeus-Merzbacher-like disease (12 papers, 2012 to 2025). Pelizaeus-Merzbacher like disease (PMLD) is an autosomal recessive leukodystrophy sharing identical clinical and radiological features as X-linked Pelizaeus-Merzbacher disease (PMD). "Mutations in GJC2 lead to three distinct phenotypes, Pelizaeus Merzbacher like disease, hereditary spastic paraparesis (SPG44) and subclinical leukodystrophy." (PMID 37189458, 2023). "Others have shown that splicing mutations in GJC2 encoding Cx47 can cause a severe form of Pelizaeus-Merzbacher-like disease." (PMID 29701678, 2018). "For example, null mice for Cx47 or homozygous Cx47M282T/M282T mice show only mild myelin deficits, contrary to human patients with mutations in its human ortholog, GJC2, which causes Pelizaeus-Merzbacher-like disease." (PMID 28407788, 2017). "Mutations in the GJA12/GJC2 gene cause one form of autosomal recessive Pelizaeus--Merzbacher-like disease." (PMID 25035705, 2014). "Loss-of-function mutations in the Cx47 gene (GJA12/GJC2) lie at the basis of Pelizaeus-Merzbacher-like disease (PMLD1), an early onset, progressive dysmyelinating disorder affecting the CNS, and are also known to cause a distinct form of late onset hereditary spastic paraplegia (SPG44)." (PMID 24133447, 2013). "First, mutations in human GJC2, coding for gap junction protein gamma-2 (OMIM 608803), are the cause of hypomyelinating leukodystrophy 2 (OMIM 608804), lymphatic malformation 3 (OMIM 613480), and autosomal recessive spastic paraplegia 44 (OMIM 613206)." (PMID 37588046, 2023). "GJC2/Cx47 mutations cause HLD2, also known as Pelizaeus-Merzbacher-like disease (PMLD), an early onset dysmyelinating disorder characterized by nystagmus, psychomotor retardation, progressive spasticity and cerebellar signs." (PMID 31232168, 2019). "Substitutions of highly conserved amino acids in GJC2 (Cx47) cause LE in all four extremities, whereas loss-of-function mutations cause Hypomyelinating leukodystrophy 2 (OMIM 608804), in which LE does not occur." (PMID 33844116, 2021).
leukodystrophy (10 papers, 2011 to 2025). Leukodystrophies are a group of rare, progressive, metabolic, genetic diseases that affect the brain, spinal cord and often the peripheral nerves. "Pelizaeus‐Merzbacher‐like disease, caused by biallelic pathogenic variants in the GJC2 gene (encoding Cx47), is associated with hypomyelinating leukodystrophies observed on brain MRI, neurodevelopmental delay, and epilepsy in some cases." (PMID 41299860, 2025). "For instance, mutations in the gene coding for Cx47 (GJC2) give rise to a hypomyelinating leukodystrophy." (PMID 36140338, 2022). "PMLD1 is a slowly progressive leukodystrophy caused by mutations in the gene GJC2 that encodes Cx47." (PMID 36140338, 2022). "Of note, one patient with a PKD1 variant was affected also by GJC2 leukodystrophy." (PMID 39384646, 2025). "Other variants with a founder effect have been reported with hypomyelinating leukodystrophies in the Tunisian population, such as the GJC2 variant c.‐167A>G in Tunisian patients with PMLD disease, and the FAM126 variant c.414 + 1G>T in Tunisian patients with hypomyelination and congenital cataract." (PMID 39436788, 2024). "Pelizaeus-Merzbacher like disease (PMLD) is a hypomyelinating leukodystrophy with very similar clinical manifestation to PMD but caused by autosomal recessive loss-of-function mutations in the gap junction protein connexin 47 (GJC2) gene." (PMID 34239416, 2021). "Utilizing the Cx32/Cx47 dKO model of HLD2, we examined whether GJC2/Cx47 gene replacement specifically in oligodendrocytes would provide a therapeutic approach for this type of leukodystrophy." (PMID 31232168, 2019).
primary lymphedema (7 papers, 2017 to 2026). A congenital condition that results in swelling in the arms or legs, and can occur during adolescence or adulthood. "GJC2 encodes for connexin-47 (Cx47) and is a causally mutated in some forms of human primary lymphedema." (PMID 38743922, 2024). "In this study, we quantified the VV defects in the limbs of patients with primary lymphedema caused by mutations in GJC2 or FOXC2 and examined the earliest underlying mechanisms of VV failure caused by loss of those genes in mice." (PMID 28724617, 2017). "Mutations in the genes encoding FOXC2, (FOXC2) CX47 (GJC2), and CX43 (GJA1) cause primary lymphedema in man." (PMID 28724617, 2017). "Mutations in the gene encoding for the gap junction protein Cx47 (GJC2) have been described as causal variants in primary lymphedema; however, the expression of GJC2 mRNA was not significantly changed in cultured hLECs upon treatment with CGRP for 8 hours." (PMID 38743922, 2024).
Ataxia (5 papers, 2019 to 2023). Ataxia refers to impaired coordination of voluntary muscle movement. "Another demyelinating disease associated with mutations in the GJC2 gene coding for connexin 47 (Cx47) is Pelizaeus-Merzbacher-like disease type 1 (OMIM #608804), characterized by progressive spasticity and ataxia." (PMID 31780897, 2019). "Loss of function mutations in the GJC2 gene encoding Cx47 result in hypomyelinating leukodystrophy Type 2 (HLD2) characterized by abnormal CNS myelin formation and progressive degeneration, as well as nystagmus, progressive spasticity, and ataxia." (PMID 31232168, 2019).
hypomyelinating leukodystrophy 2 (5 papers, 2011 to 2023). Any leukodystrophy in which the cause of the disease is a mutation in the GJC2 gene. "Hypomyelinating leukodystrophy type 2 (HLD2), is an inherited genetic disease of the central nervous system caused by recessive mutations in the gap junction protein gamma 2 (GJC2/GJA12)." (PMID 35794704, 2022).
hereditary spastic paraplegia (3 papers, 2011 to 2023). Hereditary spastic paraplegias (HSP) comprise a genetically and clinically heterogeneous group of neurodegenerative disorders characterized by progressive spasticity and hyperreflexia of the lower limbs. "The milder late onset hereditary spastic paraplegia (SPG44, MIM: 613206) is associated with another recessive missense mutation I33M in the GJC2 gene." (PMID 21750683, 2011).
epilepsy (1 paper, 2025). A brain disorder characterized by episodes of abnormally increased neuronal discharge resulting in transient episodes of sensory or motor neurological dysfunction, or psychic dysfunction. "Calcium pathway scoring, based on epilepsy‐induced gene sets, paralleled Gjc2 distribution, with the strongest enrichment in HSPOL, Earlyres.OL, and StressOL." (PMID 41299860, 2025).
lymphatic disorders (1 paper, 2021). "Whether we will be able to target Cxs for the treatment of lymphatic disorders will very much depend on the unraveling of the effects of the GJC2 and GJA1 gene mutations (and maybe in the future also GJA4 and Panx1 gene mutations) in relevant in vitro, ex vivo and in vivo models." (PMID 34072103, 2021).
rheumatoid arthritis (1 paper, 2021). A chronic, systemic autoimmune disorder characterized by inflammation in the synovial membranes and articular surfaces. "CCBE1 ADAMTS3, VEGFC, FLTR4, and GJC2 are thought to be related with either Hennekam disorder or its related symptoms in many diseases, including rheumatoid arthritis." (PMID 34234628, 2021).
peripheral nervous system disease (1 paper, 2023). "A number of these, including connexin 26 (Cx26)/GJB2, Cx29/Cx31.3/GJC3, Cx30/GJB6, Cx32/GJB1, Cx36/GJD2, Cx43/GJA1, Cx45/GJC1 and Cx47/GJC2 are expressed in the central and/or peripheral nervous system and mutations in a number of these cause central and/or peripheral nervous system disease." (PMID 37189458, 2023).
GJC2 also shares sentences with these, for which no sentence is quoted: breast carcinoma (4 papers); demyelinating disease (4); experimental autoimmune encephalomyelitis (4); multiple sclerosis (4); Alzheimer disease (3); atherosclerosis (3); Leukoencephalopathy (3); Nystagmus (3); amyotrophic lateral sclerosis (2); cancer (2); infection (2); Pelizaeus-Merzbacher Disease (2); viral infection (2); Alexander disease (1); Anxiety (1); autosomal recessive spastic paraplegia 44 (1); Barrett esophagus (1); choanal atresia (1); Chylothorax (1); colorectal cancer (1); demyelination (1); developmental delay (1); dysplasia (1); Encephalopathy (1); hereditary lymphedema III (1); hyperlipidemia (1); lymphangiectasia (1); lymphatic malformation 3 (1); movement disorder (1); neoplasia (1).
A further 10 diseases each share a sentence with GJC2 in 1 paper.